HLA-G (major histocompatibility complex, class I, G)
Diseases named in the same sentence as HLA-G in open-access papers (continued):
Sharing a sentence is not in itself a finding about the gene and the disease.
cervical carcinoma (continued). "Thus, the role of HLA-G in malignancies has gained considerable clinical interest due to the possibility of exploiting it as a novel diagnostic/prognostic biomarker to identify cervical cancer and to monitor disease stage." (PMID 32670296, 2020). "Genetic polymorphism of HLA‐G and FOXP3 was assessed in 55 cervical cancer patients with clinical follow‐up, relapse, or death, and compared to 126 healthy controls." (PMID 41263059, 2025). "Recently, an eight-gene prognostic model constructed on the basis of HLA-G-driven differential genes demonstrated good predictive value for the prognosis of cervical cancer patients (AUC = 0.896)." (PMID 38310272, 2024). "HLA-G has been implicated in malignant transformation, increasing throughout CIN progression and peaking in cervical cancer." (PMID 38310272, 2024). "HLA-G expression is strongly related to higher tumor grade and worse prognosis for patients with cervical cancer." (PMID 36618382, 2022). "HLA-G-driven differentially expressed genes (DEGs) were obtained from two cervical carcinoma cell lines, namely, SiHa and HeLa, with stable overexpression of HLA-G by RNA sequencing (RNA-seq)." (PMID 35924232, 2022). "The eight HLA-G-driven DEG signatures of our prognostic model suggested great ability in predicting the overall survival of patients with cervical cancer." (PMID 35924232, 2022). "Our previous and current findings enhance our understanding of HLA-G polymorphisms, which are not only associated with susceptibility to HPV infection but also involved in the susceptibility to and progression of cervical cancer by affecting sHLA-G levels." (PMID 36618382, 2022). "In HPV-associated tumors like cervical cancer and head and neck squamous cell carcinoma (HNSCC), a role of HLA-G in HPV infections and in the initiation and progression has been described mediated by polymorphisms, methylation and deregulation of HLA-G." (PMID 35237271, 2022). "HLA-G polymorphisms are genetic susceptibility and/or disease-relevant factors for cervical HPV infections and viral persistence of cervical cancers." (PMID 35237271, 2022). "It has been reported that HLA-G/sHLA-G is highly expressed in the tissues or peripheral blood of cervical cancer patients, contributing to the immune escape of cancer cells." (PMID 36618382, 2022). "Twenty-eight genes selected from LASSO were then used to identify key predictors of HLA-G-driven DEGs in the prognostic model for predicting the overall survival of cervical cancer patients by stepwise multivariate Cox regression." (PMID 35924232, 2022). "Few studies showed HLA-G*01:01:01, -*01:01:03, and -*01:01:05 and the HLA-G 14bp deletion to be associated with HPV infection or cervical cancer among women." (PMID 35363864, 2022). "It has been reported that cervical CSCs secrete high levels of HLA-G and are suggested to be potent immune modulators that favor cervical cancer cell survival." (PMID 33971970, 2021). "Overall, the discrepancies in these studies that examined HLA-G expression in cervical cancer patients are partly due to tumor heterogeneity." (PMID 32670296, 2020). "Several studies have investigated the relationship between HLA-G isoform expression and clinicopathologic features in patients with precancerous lesions and invasive cervical cancer." (PMID 32670296, 2020). "The HLA-G*01:01:02, HLA-G*01:06 and 3′UTR 14bp Ins alleles were associated with disease progression from preinvasive to invasive cervical cancer among HPV-positive Canadian women." (PMID 32670296, 2020). "Human leukocyte antigen (HLA)-G is an immune checkpoint molecule, which expression in cervical cancer cells enables them to escape immunosurveillance." (PMID 30619504, 2018). "In a cohort of 136 patients, HLA-G expression (probing with mAb 4H84) was detected in 25% of the primary cervical cancers and in 11% of paired metastatic LNs." (PMID 30319626, 2018).
cervical carcinoma (continued). "Most cervical cancer cell lines, however, barely express HLA-G at the mRNA level and minimally express HLA-G on the cell surface, which makes studying HLA-G more complicated." (PMID 28402962, 2017). "We investigated the HLA-G expression levels in iRCs and found that iRCs expressed significantly higher levels of HLA-G mRNA than the cervical cancer cell line CaSki (p = 0.0032)." (PMID 28402962, 2017). "Within the context of cervical cancer, HLA-G expression has been correlated with disease progression in patients with cervical cancer." (PMID 25351636, 2015). "Recent evidence showed that HLA-G expression increased with grade of precancerous cervical lesions, with the highest expression found in cervical cancer." (PMID 23265140, 2012). "However, among these previous studies of cervical cancer, the expression of HLA-G was mainly evaluated in the cell membrane (mHLA-G) of malignant lesions, and much less attention was given to its secretion as soluble HLA-G (sHLA-G) into the bodily fluids." (PMID 36053326, 2023). "Therefore, it would be worthwhile to monitor the dynamic process of sHLA-G and cytokines in patients with cervical cancer and explore anti-HLA-G-based immunotherapy strategies for breaking down tolerance in cancer." (PMID 36053326, 2023). "Finally, we selected the overlapping genes in the upregulated group and downregulated group, including 391 upregulated genes and 717 downregulated genes, which were identified as HLA-G-driven DEGs in cervical cancer." (PMID 35924232, 2022). "Here, we focused on evaluating the possible association of HLA-G 3’UTR polymorphisms with sHLA-G plasma levels in the Chinese Han population and its value in clinical prognostic evaluation and survival outcome prediction in patients with cervical cancer." (PMID 36618382, 2022). "On the one hand, HLA-G expression might serve as a marker of malignancy in cervical cancer, both the HLA-G membrane form expressed by cervical cancer cells and the HLA-G soluble form identified in blood serum." (PMID 36010256, 2022). "The progressive upregulation of HLA‐G may be an important factor in the maintenance of HPV conducive to cervical cancer." (PMID 35759240, 2022). "Also, lncRNA HOTAIR promotes the expression of HLA-G in both gastric and cervical cancer by sponging two different miRNAs; miRNA-152 and miRNA-152, respectively." (PMID 36207500, 2022). "These functional annotations suggested possible pathways or functional imbalances in which HLA-G-driven DEGs might be involved in the process of cervical cancer." (PMID 35924232, 2022). "Interestingly, lncRNA HOTAIR enhances immune escape and tumor progression of both gastric cancer and cervical cancer by promoting the expression of human leukocyte antigen (HLA)-G." (PMID 36207500, 2022). "Many studies have analyzed HLA-G expression in cervical cancer patients." (PMID 36010256, 2022). "Particular HLA-G diplotypes are related to the cervical cancer outcome." (PMID 36618382, 2022). "The long non-coding RNA HOX transcript antisense RNA (HOTAIR) may also serve as a competing endogenous RNAs (ceRNAs) to regulate HLA-G expression by sponging miR-148a in cervical cancer cells." (PMID 32670296, 2020). "Targeting the HOTAIR-miR-148a-HLA-G axis or HLA-G-specific miRs could represent a novel therapeutic strategy in cervical cancer." (PMID 32670296, 2020). "HLA-G has been identified as a cervical cancer stem cell (CCSC)-specific marker, and targeting HLA-G and its related signaling pathways may offer a novel strategy for CCSC-targeted therapy." (PMID 32670296, 2020). "However, to date, the possibility that HLA-G gene polymorphisms and/or protein expression affecting HPV infection persistence and cervical cancer risk remains to be explored." (PMID 32670296, 2020).
cervical carcinoma (continued). "Another study focused on HLA-G mRNA expression in cervical cancer in Korean patients using RT-PCR (15 normal tissues and 40 cervical cancer tissues) and found that high HLA-G mRNA expression was related to the early stages of cervical cancer." (PMID 32670296, 2020). "The checkpoint molecule HLA-G with immune tolerance contribute to cervical carcinogenesis, but HLA-G could also represent a good immunotherapeutic target for cervical cancer treatment." (PMID 32670296, 2020). "Indeed, the mechanisms of HPV involvment in the modulation of HLA-G expression among different types of cervical cancer remain to be determined." (PMID 30619504, 2018). "Perhaps, the increased HLA-G level dependent of HIV infection is one of the mechanisms behind the association between HIV infection and high-risk of HPV co-infection, and increased risk of cytological abnormalities and cervical cancer." (PMID 30278059, 2018). "However, the results obtained were inconclusive and even contradictory, as the HLA-G molecule was observed differentially at either decreased or increased expression levels in cervical cancer tissues." (PMID 30619504, 2018). "HPV infection and HPV-associated cervical cancer have also been associated with the presence of polymorphic sites at the HLA-G gene, irrespective of HIV infection." (PMID 30278059, 2018). "Therefore, it will be interesting to investigate if soluble HLA-G is present in cervical cancer patients and especially, to examine if serum HLA-G and MICA altogether are able to deliver a death signal in immune cells." (PMID 18208618, 2008). "Therefore, blocking checkpoint molecule HLA-G could be used as a promising immunotherapeutic strategy for the treatment of cervical cancer." (PMID 35924232, 2022). "However, its role in HLA-G-driven differentially expressed genes (DEGs) in tumour growth and advanced-stage cervical cancer remain unknown." (PMID 35924232, 2022). "The results of both studies further showed that Interleukin-10 (IL-10) expression was also significantly increased in cervical cancer tissues, which supports a shift toward a Th2 cytokine microenvironment; this in turn may promote local immunosuppression by upregulating HLA-G expression." (PMID 32670296, 2020). "The HLA-G 3’UTR diversity has only been evaluated in patients with HPV mono-infection, including the 14-bpdel/+3142C haplotype in Italian women, and the +3142C allele in Taiwanese women, which were associated with increased risk for developing HPV cervical cancer." (PMID 30278059, 2018). "However, the clinical relevance of HLA-G in cervical cancer needs to be further explored." (PMID 30619504, 2018). "However, we might say that using iRCs or iPSCs could be a good model and method to investigate the characteristics of HLA-G, and to obtain insight into cervical cancer stem cells." (PMID 28402962, 2017). "A progressive increase in HLA‐G protein expression in the HPV‐infected cervix and cervical carcinoma has been reported." (PMID 35759240, 2022). "Meanwhile, in cervical cancer, HOTAIR triggers the expression of HLA-G by directly sponging and inhibiting miRNA-148a." (PMID 36207500, 2022). "Thus, HLA-G could serve as a novel immune checkpoint molecule and play a key role in novel immunotherapy approaches that offer a promising perspective for tumor progression and advanced- stage cervical cancer." (PMID 32670296, 2020). "In this review, we aim to summarize and discuss the immunologic role of the HLA-G molecule in the context of HPV infections and the process of cervical cancer carcinogenesis." (PMID 32670296, 2020). "Immunotherapy targeting the PD-1/PD-L1 has been successful in advanced cervical cancer, but the potential clinical value of other checkpoint molecules remains unknown, such as TIM-3/LGALS9 or HLA-G/ILT2." (PMID 35924232, 2022).
cervical carcinoma (continued). "It is well-known that the HLA-G molecule is a novel biomarker and potential therapeutic target that is relevant in various types of cancers, but its role in cervical cancer has not been fully explored." (PMID 32670296, 2020). "We also investigated iRC expression of human leukocyte antigen-G (HLA-G), which is involved in cervical carcinogenesis and immune tolerance but is not expressed in conventional cervical cancer cell lines at the protein level." (PMID 28402962, 2017). "No other correlations were found between cytotoxicity levels and HLA-E or HLA-G expression levels on cervical cancer cell lines (data not shown)." (PMID 27783105, 2017). "Classical (HLA-A and HLA-B/C)- and non-classical HLA molecules (HLA-E and HLA-G) were studied on primary tumors and paired lymph node (LN) metastases from cervical cancer patients (n = 136) by immunohistochemistry." (PMID 27895918, 2016). "We did not consider invasive cervical cancer in the present study, since the occurrence of HLA-G expression in cervical cancer cells is still controversial in the scientific literature." (PMID 23265140, 2012). "Some authors reported variable HLA-G expression in cervical cancer cells, others very low or no expression, suggesting that if methylation status plays a role in promoting carcinogenesis, it probably acts in the early phases, rather than in the advanced phases of the process." (PMID 23265140, 2012). "The results of all three studies indicated that HLA-G expression was negative in normal or adjacent non-tumorous tissues but was significantly increased along with CIN grade and cervical cancer metastasis." (PMID 32670296, 2020). "In addition, immune checkpoint HLA-G expression was negative in normal or adjacent non-tumorous tissues but was significantly increased along with CIN grade and cervical cancer metastasis, especially in HPV-infected tissues." (PMID 36053326, 2023).
gastric cancer (29 papers, 2015 to 2025). A primary or metastatic malignant neoplasm involving the stomach. "Among the common alleles examined, HLA-G*01:01:01 was identified as a significant genetic factor associated with gastric cancer." (PMID 39408976, 2024). "The results of this study are significant as this is the first instance where the HLA allelic profile of a non-classical gene, crucial in cancer immune evasion, has been associated with HLA-G in a cohort of Spanish gastric cancer patients." (PMID 39408976, 2024). "The combination of a low p-value and a high odds ratio confirms a statistically significant association between HLA-G*01:01:01 and gastric cancer." (PMID 39408976, 2024). "The Fisher’s exact test revealed a remarkably low p-value of 0.0014, strongly indicating a significant association of HLA-G*01:01:01 with gastric cancer." (PMID 39408976, 2024). "This study shows that individuals harboring genetic markers in the 3’UTR region associated with elevated HLA-G expression are more susceptible to developing gastric cancer." (PMID 39549048, 2024). "In gastric cancer, HLA-G overexpression associates with immune escape and correlates with a local increase of T regulatory cells (TREGs)." (PMID 30899759, 2019). "Some studies have also indicated human leukocyte antigen (HLA)-G-associated immune escape involving TGF-β management in gastric cancer (GC)." (PMID 26627200, 2015). "Increased HLA-G level has been also reported in GC patients, and HLA-G-positive gastric cancers are often associated with poor survival." (PMID 26627200, 2015). "Many studies have reported the association between HLA-G-positive gastric cancer patient and poor survival, with a recent study suggesting the tumor escape mechanism by increasing Foxp3 + Treg lymphocytes and decreasing CD8 + T lymphocytes in GC." (PMID 26627200, 2015). "Our results clearly show that HLA-G polymorphisms are linked to gastric cancer susceptibility." (PMID 34557189, 2021). "We conclude that the polymorphisms 14bp INS/DEL and +3142 C/G of the HLA-G gene mediate gastric cancer risk and survival, and suggest the possibility of establishing new therapeutic approaches aiming at counterbalancing the negative role of this protein in tumors." (PMID 34557189, 2021). "This new association of HLA-G*01:01:01 with gastric cancer and its potential use as a predictive biomarker of disease should be taken into consideration together with other classical gastric cancer predictive markers such as CEA and CA-19-9, commonly used in clinical practice." (PMID 39408976, 2024). "Moreover, HLA-G associated immune escape in gastric cancer might be mediated by suppressing CD8+ T lymphocytes and increasing local Foxp3+ regulatory T (Treg) cells." (PMID 26627200, 2015). "In this study, HLA-G expression in 523 gastric cancer (GC) lesions and 283 case-matched peritumoral tissues (PTTs) was analyzed by immunohistochemistry." (PMID 41181133, 2025). "In summary, our preliminary findings revealed, for the first time, that HLA-G expression is restricted to fundic gland mucous neck cells and that HLA-G expression in PTTs is significantly related to the poor survival of patients with gastric cancer." (PMID 41181133, 2025). "Our principal component analysis (PCA) revealed that HLA-G*01:01:01 exhibited a strong correlation with PC1 and PC2, again suggesting a potential role in gastric cancer susceptibility." (PMID 39408976, 2024). "For example, the lncRNA, HOTAIR induces HLA-G expression by silencing the miR-152 in gastric cancer." (PMID 39355248, 2024). "Further research is needed comparing a larger cohort to assess the role of HLA-G*01:01:01 in gastric cancer development and progression." (PMID 39408976, 2024). "High-expressor HLA-G 3’UTR haplotypes (UTR-1 and UTR-6) were significantly associated with gastric cancer susceptibility, indicating a potential role in tumor immune evasion." (PMID 39549048, 2024).